EGFR (epidermal growth factor receptor)
Diseases named in the same sentence as EGFR in open-access papers (continued):
Sharing a sentence is not in itself a finding about the gene and the disease.
adenocarcinoma (continued). "The univariate Cox regression analysis revealed that some factors, including male sex, smoking, a high pathological stage, the EGFR-wild-type status, and a high score for SPP1 on TAMs, were associated with a shorter CSS in adenocarcinoma." (PMID 36139536, 2022). "Many oncogenic drivers of adenocarcinoma have been found in the clinic, such as the epidermal growth factor receptor (EGFR) and anaplastic lymphoma kinase (ALK)." (PMID 34845836, 2022). "Compared with EGFR‐negative cases, the most were female (χ2 = 45.938, P < 0.001), non‐smoking (χ2 = 51.838, P < 0.001), and adenocarcinoma (χ2 = 37.731, P < 0.001) patients in the EGFR‐positive group." (PMID 35081265, 2022). "Targetable driver mutations such as EGFR, ALK, or ROS1 alterations are exclusively found in adenocarcinoma histology." (PMID 36214468, 2022). "Regarding the adenocarcinoma group, the main mutations were ALK (Ile1461Val) in 95.24% of patients, EML4 (Lys398Arg) in 47.62% of the patients, and EGFR (Arg521Lys) and ROS (Arg167Gln) in 42.86% of the patients." (PMID 36422072, 2022). "In the EGFR‐positive group, the majority were female (χ2 = 61.934, P < 0.001), non‐smoking (χ2 = 59.315, P < 0.001), and adenocarcinoma (χ2 = 44.864, P < 0.001) patients." (PMID 35081265, 2022). "Of 49 patients experiencing a disease relapse (21.7% of all population), 6 (12.2%) patients had an EGFR mutant adenocarcinoma and 43 (87.8%) were EGFR wild type." (PMID 35847912, 2022). "In the adenocarcinoma group, the main mutations were ALK (Ile1461Val), in 95.24% of patients, EML4 (Lys398Arg) in 47.62% of the patients, and EGFR (Arg521Lys) and ROS (Arg167Gln) in 42.86% of the patients." (PMID 36422072, 2022). "Several studies have indicated that ROS1 translocation usually occurs in EGFR wild-type adenocarcinomas." (PMID 35628598, 2022). "Among two cases with EGFR mutations in the NGS assay, one case had p-stage IVB adenocarcinoma with an L858R point mutation in the LAMP assay, while the other had p-stage IIIA adenocarcinoma with an L858R point mutation only in the NGS assay." (PMID 35744511, 2022). "This study included 478 patients with PLC (348 adenocarcinomas and 130 other histological types) who underwent surgical resection and EGFR gene testing." (PMID 36115683, 2022). "First, we examined the expression of NF-κB components, AICDA, Akt, JAK2/STAT3, and IL6 in PC9 (adenocarcinoma with the EGFR exon 19 deletion) and PC9/GR (adenocarcinoma with the EGFR-TKI-resistant with T790M mutation) cells, using Western blotting and RT-PCR." (PMID 35740609, 2022). "In adenocarcinoma, female patients had significantly higher prevalence of EGFR exon 19 deletion and L858R compared to male patients." (PMID 35061839, 2022). "Case #4 is a patient with an EGFR del19 adenocarcinoma who was treated with erlotinib and developed EGFR T790M." (PMID 36153311, 2022). "Multiple clinical studies have already demonstrated that SQCC patients are generally less sensitive to EGFR-TKI therapy than those with adenocarcinoma." (PMID 35984168, 2022). "Interestingly, it was found that the 7-AABs positive group was associated with higher proportion of EGFR mutations (P<0.001), lower pathological differentiation degrees (P=0.018), more advanced pathological stages (P=0.040) and higher Ki-67 indexes (P=0.011) in patients with adenocarcinoma." (PMID 36531072, 2022). "Although EGFR-TKIs had great therapeutic efficacy in early-stage adenocarcinoma, little improvement in late stages (stage III, stage IV) was observed in this study." (PMID 36233370, 2022). "This retrospective study evaluated the efficacy of adding anti-PD1/L1 or anti-VEGF therapy to platinum-based chemotherapy in EGFR-TKI-resistant EGFR-mutant adenocarcinoma patients in a single center and real-world setting." (PMID 35884533, 2022). "This patient was a 58-year-old woman diagnosed with stage IV adenocarcinoma of the lung carrying an EGFR exon 19 deletion." (PMID 35326664, 2022).
adenocarcinoma (continued). "The aim of this study was to identify the relationships of epidermal growth factor receptor (EGFR) mutations and anaplastic large-cell lymphoma kinase (ALK) status with CT characteristics in adenocarcinoma using the largest patient cohort to date." (PMID 33707479, 2021). "Our study provides evidence of a shorter PFS in EGFR-mutant SCC compared to EGFR-mutant adenocarcinoma patients." (PMID 34195081, 2021). "Primary tumor resection was associated with improved survival in patients with occult intraoperatively-confirmed M1a adenocarcinoma receiving EGFR-TKIs." (PMID 33954108, 2021). "The heatmap shows the inter-cell-line heterogeneity of the adenocarcinoma cells while the following markers showed the highest expression in the panel: EGFR and CD24 in the case of A549; CD326 and CD274 for H1975; and CD326 and EGFR for H1650." (PMID 35008313, 2021). "The TRU-type adenocarcinoma is characterized by TTF-1 (thyroid transcription factor-1) expression and EGFR (epidermal growth receptor factor) mutations." (PMID 34679600, 2021). "Of note, the TSHZ2 expression was negatively correlated with the EGFR expression in most adenocarcinoma cells except for H1573 adenocarcinoma cells." (PMID 33850468, 2021). "This study aimed to identify novel genetic variants in the CR2 extracellular domain of the epidermal growth factor receptor (EGFR) in healthy individuals and patients with six different types of adenocarcinoma, in Arabian peninsula populations." (PMID 33874989, 2021). "We detected a significantly higher EGFR level in sEVs derived from a PE sample of a patient with an EGFR-driven NSCLC adenocarcinoma than in sEVs from PE samples of non-EGFR driven adenocarcinoma patients or in samples from patients with benign lung disease." (PMID 33671772, 2021). "All patients had adenocarcinoma histology, stage IV disease at diagnosis and were pretreated with EGFR-TKIs." (PMID 33919291, 2021). "One study reported that specimens obtained via RP‐EBUS‐TBLB using a 1.8‐mm diameter biopsy forceps allowed analyses of EGFR mutational status, and ALK and PD‐L1 IHC, in more than 90% of adenocarcinoma cases." (PMID 33949136, 2021). "Among the EGFR-mutant adenocarcinoma patients, 19 (64.3%) harbored 19Del, and 22 (53.7%) harbored L858R changes." (PMID 34195081, 2021). "Our results suggest that BRAF-mutant clones are enriched through EGFR-directed therapy in EGFR-mutant adenocarcinoma." (PMID 34921211, 2021). "In this study, acquired T790M mutation was identified at the time of rebiopsy in approximately 40% of patients with EGFR‐mutant adenocarcinoma who were treated with EGFR‐TKI." (PMID 33529490, 2021). "The HBcAg engineered to present affibody and tags (HAF) bound specifically to EGFR and exterminated the EGFR-overexpressing adenocarcinomas under alternating magnetic field (AMF) after binding with gold ions." (PMID 34502049, 2021). "Improved DFS in most of the trials with adjuvant EGFR-TKIs in EGFR mutant patients in stage IB-IIIA adenocarcinoma (for example ADAURA trial) promises the change of current practice in these patients." (PMID 34830123, 2021). "An inhibitor of EGFR, afatinib is a second-generation small-molecule inhibitor that also targets the EGFR pathway NSCLC adenocarcinomas with activating EGFR mutations that are eligible for therapy with these drugs." (PMID 34607478, 2021). "On the other hand, recent studies showed the impact of molecular differentiation on positive EGFR adenocarcinoma with targeted therapy, as it became essential for future therapeutic plans." (PMID 34963835, 2021).
adenocarcinoma (continued). "HAF complexed with gold ions (HAFG) showed negligible cytotoxicity, and destroyed EGFR-overexpressing adenocarcinoma cells via the hyperthermia effect under AMF." (PMID 34502049, 2021). "Regarding EGFR mutation and ALK translocation in adenocarcinoma, seven cases were L858R positive, three cases were exon 19 positive, one case was ALK positive, and 12 cases were wild type." (PMID 35201464, 2021). "The 25 stage IV adenocarcinoma patients consisted of 18 females and seven males, harboring a deletion in exon 19 of the EGFR gene." (PMID 34441254, 2021). "Our case highlights the possibility of SCLC transformation from EGFR-mutant adenocarcinoma and the importance of repeat biopsy for drug resistance." (PMID 34397927, 2021). "Overall, EGFR-mutant SCC showed similar gene characteristics to EGFR-mutant adenocarcinoma, but different ones to EGFR wild-type SCC." (PMID 34195081, 2021). "We observed a higher mutation frequency of NF1, ATR, and BRCA1 in EGFR-mutant SCC compared to EGFR-mutant adenocarcinoma." (PMID 34195081, 2021). "We also evaluated EGFR expression levels on sEVs from PE samples from patients with benign lung disease in comparison to sEVs from MPE fluid from patients with NSCLC adenocarcinoma." (PMID 33671772, 2021). "Regarding mutation characteristics at the arm-level, the total number of arm deletions (P=0.380) and arm amplifications (P=0.307) was identical between EGFR-mutant adenocarcinoma and SCC." (PMID 34195081, 2021). "Among the patients with EGFR mutations, shorter progression-free survival (PFS) was observed in SCC compared to adenocarcinoma (4.6 vs. 11.0 months, P<0.001)." (PMID 34195081, 2021). "Most of them (31/32, 96.9%) were adenocarcinoma, 40.6% of cases were determined by the ARMS method for EGFR mutation types, while 59.4% were identified by NGS method." (PMID 34751504, 2021). "Further studies will be required to confirm this finding and determine the efficacy and safety of molecular targeted therapy on EGFR mutant adenocarcinoma in patients with IPF." (PMID 33859288, 2021). "The adenocarcinoma cells which overexpressed EGFR were used to verify the therapeutic effect of HAF complexed with gold ions (HAFG)." (PMID 34502049, 2021). "There are significant differences in CTR, gender and smoking history between EGFR mutant and EGFR wild-type adenocarcinoma." (PMID 34804960, 2021). "The importance of molecular targeting (identifying presence of mutations) cannot be understated as there is evidence for mutual exclusiveness between EGFR-activating mutations and KRAS mutations that are often seen in adenocarcinoma." (PMID 34439273, 2021). "The majority of the patients had adenocarcinoma (94.7%), ECOG-PS 0 – 1 (82.6%), and sensitising EGFR mutations (95.1%)." (PMID 34798865, 2021). "Of the 12 cases of adenocarcinoma, 11 (91.7%) had adequate samples for all molecular tests including EGFR, ALK, and PD-L1." (PMID 34441366, 2021). "Between EGFR-mutant SCC and EGFR-mutant adenocarcinoma, the observation of similar genomic patterns presents, we are unable to adequately identify the unambiguous mechanism underlying the blunted responsiveness." (PMID 34195081, 2021). "EGFR mutation rate varies in different pathological types, and the mutation in ADC was more than that in non-adenocarcinoma." (PMID 35049681, 2021). "The mass was biopsied via bronchoscopy, and histopathological examination (HPE) results showed an adenocarcinoma favoring a primary lung malignancy, which showed a deletion in exon 19 of the epidermal growth factor receptor (EGFR) gene." (PMID 33618728, 2021). "In conclusion, our study showed that EGFR-mutant lung SCC patients responded poorly to EGFR-TKI treatment compared to the EGFR-mutant adenocarcinoma patients." (PMID 34195081, 2021). "TMB was comparable between EGFR-mutant SCC and adenocarcinoma patients (7.61 vs. 5.99 mutations/Mb, P=0.565), the median TMB (mTMB) was 7.61 (95% CI: 5.84–13.40) and 5.99 (95% CI: 5.77–11.13) mutations/Mb, respectively." (PMID 34195081, 2021).
adenocarcinoma (continued). "EGFR mutation-positive NSCLC is common in East Asia, and approximately 50% of adenocarcinomas harbor EGFR mutations." (PMID 34831415, 2021). "The study included 118 plasma samples from a retrospective cohort of 25 stage IV adenocarcinoma patients with EGFR exon 19 deletions (Ex19Del), obtained before and during tyrosine kinase inhibitor (TKI) treatment." (PMID 34441254, 2021). "Somatic gain-of-function mutations affecting the tyrosine kinase (TK) domain of EGFR are common in NSCLC, particularly adenocarcinoma, and predict responsiveness to EGFR-targeting tyrosine kinase inhibitors (TKIs)." (PMID 34274969, 2021). "A study published in 2017 demonstrated that YAP acts as an EGFR downstream signalling molecule, modulating lung cell proliferation, and is a potential therapeutic target for EGFR-dependent adenocarcinomas." (PMID 32104210, 2020). "Compound 18 was evaluated for its antiproliferative activity against A549, adenocarcinoma human alveolar basal epithelial cell line, which overexpresses HER2 and possesses wild type EGFR and KRAS mutation." (PMID 32922539, 2020). "We report a case of a patient in whom EGFR T790M-positive adenocarcinoma transformed into LCNEC after osimertinib therapy." (PMID 32762742, 2020). "Our findings highlight that the therapeutic regimen should be adjusted for wild-type EGFR patients with poorly differentiated adenocarcinoma treated with chemotherapy to provide better outcomes." (PMID 33218158, 2020). "These cells have wild type EGFR and KRAS mutation and are present in about 30% of adenocarcinoma 43-45." (PMID 32922539, 2020). "The prevalence and clinical relevance of EGFR/ALK co-alterations in multifocal adenocarcinomas required detailed investigation as well." (PMID 32375829, 2020). "Our findings highlight that the therapeutic regimen should be adjusted for EGFR Wild-type patients with poorly differentiated adenocarcinoma treated with chemotherapy to provide better outcomes." (PMID 33218158, 2020). "In 2013, a case of adenocarcinoma lung with EGFR exon 20 insertion A763_Y764insFQEA has been reported, which was responsive to erlotinib that was added to gemcitabine, docetaxel, and vinorelbine regimen." (PMID 32622356, 2020). "Our study showed that in a cohort of patients with advanced adenocarcinomas, patients with ROS1-rearranged tumors exhibit characteristic clinical and radiologic features compared to those with EGFR mutations or ALK rearrangement." (PMID 33005033, 2020). "In summary, despite shared clinical and imaging features, ROS1-, ALK-, and EGFR-positive advanced adenocarcinomas differ in certain imaging features of the primary tumor and disease spread patterns." (PMID 33005033, 2020). "A multivariable logistic regression model was applied to determine the clinical and CT characteristics that can discriminate between ROS1-rearranged and EGFR-mutant or ALK-rearranged adenocarcinomas." (PMID 33005033, 2020). "We report a rare case of a patient in whom EGFR T790M-positive adenocarcinoma transformed into large-cell neuroendocrine carcinoma (LCNEC) after osimertinib therapy." (PMID 32762742, 2020). "Not only among invasive subtypes but among all the LUAD subtypes, lepidic adenocarcinoma subtype (LPA) had the most EGFR mutations, with 78.9% (15/19) EGFR positive patients (P = 0.003) with the majority being sensitizing mutations." (PMID 31692283, 2020). "Histopathologically, our CMPT was diagnosed as a benign lesion; however, some reports suggest it to be a precursor of adenocarcinoma because they had confirmed BRAF, EGFR, and ALK mutations, which occur early in lung adenocarcinogenesis." (PMID 32990811, 2020). "We further analyzed the information of 23 adenocarcinoma patients received the first generation of EGFR-TKI treatment after they were told EGFRmutated." (PMID 32047821, 2020).
adenocarcinoma (continued). "Pathological examination confirmed multifocal adenocarcinoma, molecular tests revealed that the left upper lung lesion was positive for ALK rearrangement but the left lower lobe displayed EGFR mutation positive separately." (PMID 32375829, 2020). "Exosomal amphiregulin (AREG) from adenocarcinoma cells can promote osteoclast differentiation by activating epidermal growth factor receptor (EGFR) pathway." (PMID 33614495, 2020). "In contrast, the addition of genetespib to docetaxel showed no additional clinical benefit in a phase 3 trial involving patients with adenocarcinomas and wild-type EGFR." (PMID 32942617, 2020). "Subgroup analysis showed that wild-type EGFR patients with poorly differentiated adenocarcinoma treated with chemotherapy had significantly worse PFS (p = 0.011)." (PMID 33218158, 2020). "Insufficient amounts of tissue for molecular genetic analysis of epidermal growth factor receptor mutations and anaplastic lymphoma kinase rearrangements, which required additional PCNB, occurred in one case of adenocarcinoma." (PMID 32342673, 2020). "Further, sub-stratification of adenocarcinoma into EGFR-mutant and wild-type groups revealed that the prognostic powers of CEAIn and CEAPd in predicting PPS were statistically significant in the EGFR-mutant group but not in the wild-type group." (PMID 32034239, 2020). "Attending physicians adopted the strategy of “shoot first, ask later”17, 28 because they expected that EGFR‐TKIs would benefit the status of adenocarcinoma, non‐smokers, and East Asian patients." (PMID 32767461, 2020). "Here we highlight the major findings that establish the signaling environment in adenocarcinomas and are relevant to anoikis resistance, EGFR signaling, and CTCs." (PMID 32575848, 2020). "Samples from females and adenocarcinoma samples are usually tested for EGFR as a first-line test and are more likely to be positive." (PMID 33425389, 2020). "Patients with stage IIIb/IV adenocarcinoma with ROS1 rearrangement, EGFR mutations, or ALK rearrangement were retrospectively identified." (PMID 33005033, 2020). "In patients with advanced NSCLC, EGFR mutations, ALK gene fusion, RET gene fusion, younger age (≤60 years), lymph node N2‐N3 metastasis and the pathological type of adenocarcinoma are all independent risk factors for brain metastasis." (PMID 31769228, 2020). "Resistance to EGFR inhibitors through histological transformation of lung EGFR-mutant adenocarcinoma to SCLC has been reported in 3%-14% of cases in repeated biopsies series." (PMID 35582610, 2020). "The clinical relevance of EGFR/ALK co-alterations in multifocal adenocarcinomas required detailed investigation as well." (PMID 32375829, 2020). "Their results revealed differences in mutation frequency between adenocarcinoma and SCC, and as was expected, the characteristic activating mutations of adenocarcinoma such as KRAS, HRAS, NRAS, and EGFR were identified only in 3% of SCCs." (PMID 32604993, 2020). "We report a case of a patient with EGFR T790M-positive adenocarcinoma that transformed to EGFR T790M-negative LCNEC after osimertinib therapy." (PMID 32762742, 2020). "Histologic transformation of NSCLC to SCLC has already been recognized as a crucial mechanism of acquired resistance to EGFR- or ALK-TKI in EGFR-mutated or ALK+ adenocarcinomas." (PMID 32299384, 2020). "In a recent study, 206 biopsies of EGFR TKI-resistant adenocarcinoma patients showed 21 SCLC transformed cases." (PMID 35582610, 2020). "In contrast to NSCLC, especially Adenocarcinoma, wherein discovery of targetable therapy (e.g. for EGFR, ALK1 and ROS1) has resulted in remarkable impact in the therapeutic outcomes, the genetic abnormalities in PSC are largely poorly defined." (PMID 32149365, 2020). "Consideration that 16.8% of lung non‐adenocarcinoma individuals with BM were EGFR or ALK positive, we used the adjusted Lung‐molGPA model to assess their survival." (PMID 33027555, 2020).